LSM1 (LSM1 homolog, mRNA degradation associated)
Description:
Plays a role in the degradation of histone mRNAs, the only eukaryotic mRNAs that are not polyadenylated. Probably also part of an LSm subunits-containing complex involved in the general process of mRNA degradation (By similarity).
Synonyms: CASM; YJL124C; FICUS
Tractability: PROTAC: its protein half-life has been measured.
Gene: Protein-coding gene on chromosome 8 (38,163,335 to 38,176,730, reverse strand). Ensembl gene ENSG00000175324.
Subcellular location: Cytoplasm; Cytoplasm, P-body
Subcellular location (Human Protein Atlas): Cytoplasmic bodies; Cytosol
Pathways (Reactome):
Metabolism of RNA: mRNA decay by 5' to 3' exoribonuclease
Gene Ontology:
Molecular function: protein binding; RNA binding; mRNA binding
Biological process: histone mRNA catabolic process; deadenylation-dependent decapping of nuclear-transcribed mRNA; mRNA processing; RNA splicing; RNA splicing, via transesterification reactions; nuclear-transcribed mRNA catabolic process
Cellular component: cytoplasm; nucleus; cytosol; Lsm1-7-Pat1 complex; P-body
Genetic constraint (gnomAD): Loss-of-function variants: 7 observed, 9.36 expected, observed/expected ratio (o/e) 0.75, 90% interval 0.42 to 1.4. That is too few expected variants to judge how well the gene tolerates losing a copy. Missense variants: 85 observed, 89.18 expected, observed/expected ratio (o/e) 0.95, 90% interval 0.8 to 1.14. Synonymous variants: 23 observed, 32.32 expected, observed/expected ratio (o/e) 0.71, 90% interval 0.51 to 1.01.
Homologues: Orthologues: chimpanzee LSM1 (100% identical), dog LSM1 (100% identical), guinea pig LSM1 (100% identical), pig LSM1 (98% identical), mouse Lsm1 (97% identical), tropical clawed frog lsm1 (95% identical), rat Lsm1 (89% identical), zebrafish lsm1 (85% identical), Drosophila melanogaster LSm1 (59% identical), Caenorhabditis elegans lsm-1 (44% identical). Paralogues in human: LSM8 (25% identical).
Diseases named in the same sentence as LSM1 in open-access papers:
LSM1 is named in the same sentence as 40 diseases in open-access papers, as found by Europe PMC text mining. Sharing a sentence is not in itself a finding about the gene and the disease. The quoted sentences say what the papers report.
breast cancer (14 papers, 2008 to 2024). A primary or metastatic malignant neoplasm involving the breast. "Overall, our findings suggest that LSM1 upregulation is highly associated with breast cancer and that LSM1 plays an important role in tumour cancer progression." (PMID 35692083, 2022). "We further analysed the association between LSM1 shRNA/sgRNA efficacy and target gene expression levels in different breast cancer cell lines." (PMID 35692083, 2022). "We investigated the potential correlation between LSM1 expression in breast cancer and several mutations commonly seen in breast cancer and showed the correlation between LSM1 expression and six mutations from the TIMER dataset." (PMID 35692083, 2022). "We found that functional LSM1 inactivation caused by mutations and profound deletions predicted poor prognosis in breast cancer (BRCA) patients." (PMID 35692083, 2022). "The association between LSM1 and immune infiltration of breast cancer was assessed by TIMER and CIBERSORT algorithms." (PMID 35692083, 2022). "In addition, LSM1 deficiency also led to a slowing of invasion of both breast cancer cells." (PMID 35692083, 2022). "Particularly, the LSM1 protein plays a role in the cellular conversion and progression of breast cancer, and pancreatic adenocarcinoma." (PMID 37007092, 2023). "For example, in breast cancer, LSM1 knockdown resulted in inhibited cell proliferation, migration, and invasion, highlighting its role in regulating tumor cell behavior." (PMID 37954131, 2023). "In this study, we analysed the value of LSM1 mRNA expression in breast cancer patients in relation to its diagnosis and prognosis using TCGA data." (PMID 35692083, 2022). "We also analysed the frequency of co‐occurrence of gene alterations with LSM1 gene alterations and found a total of 852 genes in which gene alterations co‐occurred in breast cancer." (PMID 35692083, 2022). "We additionally investigated the correlation between different immune cells and LSM1 expression in breast cancer using different algorithms." (PMID 35692083, 2022). "We also confirmed the mRNA levels of LSM1 in breast cancer cells and normal breast cells (H‐184B5F5/M10), and the results were consistent with the datasets data, where LSM1 levels were significantly higher in breast cancer cells than in normal breast cells." (PMID 35692083, 2022). "Multi‐omics analysis revealed that LSM1 mRNA expression was significantly higher in breast cancer tissues and correlated with several clinical parameters, such as high expression in ER and HER‐positive patients." (PMID 35692083, 2022). "In pharmacogenetic analysis, refametinib and trametinib treatment simulated the effects of LSM1 inhibition on breast cancer cell lines and reduced breast cancer cell growth at both high concentrations." (PMID 35692083, 2022). "We found that T cell CD8+, T cell CD4+ memory resting, myeloid DC resting and monocyte infiltration were negatively correlated with LSM1 expression in the breast cancer infiltrate cohort." (PMID 35692083, 2022). "Here, the expression of LSM1 mRNA in breast cancer was estimated using The Cancer Genome Atlas (TCGA), Oncomine, TIMER and bc‐GenExMiner databases." (PMID 35692083, 2022). "We further analysed the dependence of 57 breast cancer cell lines on LSM1 and mapped the LSM1 dependence (fold change in sgRNA abundance relative to control transfected cells) of breast cancer cell lines, which were ranked by increasing LSM1 dependence." (PMID 35692083, 2022). "LSM1 participates in the proliferation of viruses in cells and regulates their replication; it also acts as an oncogene in breast cancer (BC) after 8p11-12 amplification." (PMID 36371223, 2022). "We found that LSM1 was also highly variable and further analysed by the Oncomine database, and the expression of LSM1 gene in pan‐cancer was overexpressed in the breast cancer tissue compared to normal breast tissue." (PMID 35692083, 2022).
breast cancer (continued). "The results in different breast cancer subtypes also showed that the expression of LSM1 was lower in normal tissues than in other subtypes." (PMID 35692083, 2022). "While LSM1 was first reported to be overexpressed in breast cancer, the copy number of chromosome 8p11‐12 region was increased." (PMID 35692083, 2022). "To validate the role of LSM1 in breast cancer, we verified the expression of LSM1 in different types of breast cancer using the Oncomine dataset." (PMID 35692083, 2022). "We map the presence of splicing-related genes in breast cancer, describing three novel genes, LSM1, CLNS1A, and ILF2, that have an oncogenic role and can be modulated with BET inhibitors." (PMID 34439272, 2021). "Several studies have documented dysregulated expression of LSM1 in various cancer types, including lung cancer, prostate cancer, and breast cancer, indicating its potential as an oncogenic driver promoting tumor cell proliferation, invasion, and metastasis in multiple malignancies." (PMID 37954131, 2023). "Increased expression of LSM1 may play a role in cellular transformation and the progression of several malignancies, including lung, mesothelioma and breast cancer." (PMID 35692083, 2022). "Finally, we identified that refametinib and trametinib potentially inhibit the overexpression of LSM1 in breast cancer cells by pharmacogenomic screening of appropriate drugs and by testing different cell lines." (PMID 35692083, 2022). "Therefore, we investigated the clinical application of LSM1 to provide a basis for sensitive diagnosis, prognosis and targeted treatment of breast cancer." (PMID 35692083, 2022). "Therefore, in this study, the expression profile of LSM1 gene in breast cancer was mined and analysed through a multi‐omics strategy to analyse the biologic pathways and targets of drug candidates obtained by pharmacogenomic screening." (PMID 35692083, 2022). "Thus, Refametinib and Trametinib have anti‐cancer potential to inhibit the growth of breast cancer cells with high expression of LSM1." (PMID 35692083, 2022). "Consistently, LSM1 has been found as an oncogene activated by gene amplification and it could play a crucial role in breast cancer development and progression." (PMID 34638387, 2021). "Moreover, when the presence of CNAs in our selected genes was analyzed in different tumor types (GDC Data Portal; 67 primary sites), breast cancer was one of most frequently amplified for LSM1, CLNS1A, and ILF2." (PMID 34439272, 2021). "Regarding prognosis, the two genes of the amplicon whose mRNA hyper-expression portends adverse relapse-free survival in breast cancer are EIF4EBP1 (Eukaryotic transcription initiation factor 4E binding protein 1) and LSM1 (LSM1 homolog, mRNA degradation associated)." (PMID 32987805, 2020). "Lsm1 is a transforming oncogene that is amplified and overexpressed in breast cancer and might affect either cell cycle progression or apoptosis." (PMID 23555558, 2013). "LSM1 is located at 8p11-12 loci and is amplified in almost 20% of breast cancer cases." (PMID 19014521, 2008). "LSM1 links to macrophage, and its alterations may drive breast cancer progression." (PMID 39749323, 2024). "LSM1 is known to be involved in the general process of mRNA degradation in complexes containing LSm subunits, but the molecular and biological functions in breast cancer remain unclear." (PMID 35692083, 2022). "Therefore, targeting the LSM1 signalling axis may provide a dual role of gene suppression and immunotherapeutic response in breast cancer." (PMID 35692083, 2022). "Therefore, we speculate that high expression of LSM1 may be associated with mutations in the PIK3CA gene leading to uncontrolled cell division and recovery, which in turn affects the significant elevation of LSM1 in breast cancer." (PMID 35692083, 2022). "The results showed that the wound healing assay confirmed that LSM1 knockdown led to inhibition of migration of both MCF7 and MDA‐MB‐231 breast cancer cells." (PMID 35692083, 2022).
breast cancer (continued). "Consistently, other studies revealed LSM1, LSM2, LSM3, LSM12 as oncogenes which could play a crucial role in growth and progress of breast cancer, basal-like primary tumors, cervical carcinoma or colorectal cancer." (PMID 37007092, 2023). "Among cohorts of patients with all sub-types of breast cancer, patients with higher expression (the higher quartile of the cohorts) of EIF4EBP1 and LSM1 mRNA had worse Relapse-Free Survival (RFS) than patients with lower expression of either genes, suggesting that the two genes act as oncogenes." (PMID 32987805, 2020). "Dysregulation of LSM1 may contribute to immune evasion mechanisms employed by GBM, influencing the tumor's interaction with the immune system and shaping the immunosuppressive microenvironment, which had also been reported in breast cancer." (PMID 37954131, 2023).
lung carcinoma (5 papers, 2015 to 2023). "For example, elevated LSM1 expression in lung cancer is correlated with advanced tumor stage and reduced patient survival." (PMID 37954131, 2023). "However, in lung cancers and mesotheliomas, LSM1 protein was overexpressed compared to adjacent normal lung tissue, as measured by immunohistochemistry and western blot analysis." (PMID 36371223, 2022). "In particular, the LSM1 protein plays roles in the cellular conversion and progression of BRCA, mesotheliomas, and lung cancer, and in the metabolism of RNA." (PMID 34638387, 2021). "Moreover, LSM1 was highly correlated with “Chemoresistance pathways mediated by constitutive activation of PI3K pathway and BCL-2 in small cell lung cancer” and “IGF-1 receptor/EGFR cooperation in lung cancer”, which suggested that it also plays an important role in lung cancer tumor growth." (PMID 34638387, 2021).
pancreatic cancer (5 papers, 2016 to 2023). "LSM1 is overexpressed in 87% of human pancreatic tumor samples, and LSM1 knockout has been shown to have therapeutic efficacy in mouse pancreatic cancer models." (PMID 36371223, 2022). "LSM1 expression leads to increased growth, decreased chemosensitivity and enhanced migration/invasion of pancreatic cancer cells." (PMID 35692083, 2022). "LSM1 has been studied in other tumor types, such as pancreatic cancer, observing a role in cancer progression, metastasis, and resistance to chemotherapies." (PMID 34439272, 2021). "LSM1 was originally identified by its elevated expression in pancreatic cancer‐derived cell lines." (PMID 35692083, 2022). "Moreover, LSM1 promotes chemoresistance, transformation, and metastasis of pancreatic cancer cells." (PMID 36371223, 2022).
prostate carcinoma (5 papers, 2002 to 2024). A carcinoma that arises from epithelial cells of the prostate gland. "LSM1, also known as “CaSm” (“Cancer-associated Sm-like”), is overexpressed in various cancer, including esophageal, lung, bladder, and prostate cancer." (PMID 39417944, 2024). "No critical gene mutations were found in open reading frame of Lsm1 in prostate cancers examined by PCR–SSCP analysis, including localised and refractory cancers." (PMID 11953827, 2002). "No critical gene mutations were found in the open reading frame region of Lsm1 in 46 prostate cancer cases examined, including localized and refractory cases, by PCR–SSCP analysis." (PMID 11953827, 2002). "Meanwhile, downregulation of LSM1 is associated with prostate cancer progression." (PMID 36371223, 2022). "LSM1 downregulation is involved in prostate cancer progression, whereas amplification of the LSM1 gene in luminal BC is significantly related to poor clinical outcome and LSM1 expression was significantly related to tumor stage in BC." (PMID 36371223, 2022). "We have searched for genes differentially expressed in advanced prostate cancers using cDNA-representational difference analysis, and thereby isolated the Lsm1 as one of down-regulated gene." (PMID 11953827, 2002). "The Lsm1 gene was mapped to 8p11.2, a region which is frequently deleted in prostate cancers, using BLAST search program and down-regulation shown for refractory cancer and androgen-independent DU145 and PC3 cells." (PMID 11953827, 2002). "In contrast, LSM1 seems to play anti-tumor effects in prostate cancer." (PMID 37954131, 2023). "Recent reports demonstrated that yeast Lsm1 protein affects mRNA metabolism, particularly mRNA decapping and degradation and it is possible that human Lsm1 regulates some specific genes related to tumour invasion or metastasis in prostate cancer cells." (PMID 11953827, 2002). "The data prompted the present examination of whether Lsm1 is a target gene involved in the acquisition of androgen-independence or the metastatic phenotype in human prostate cancers." (PMID 11953827, 2002). "Therefore, clarification of the signalling cascade regulated by Lsm1 may contribute to elucidation of the molecular mechanisms responsible for acquisition of metastatic ability in human prostate cancers." (PMID 11953827, 2002). "With human prostate cancers, almost all of informative prostatectomised cases without neoadjuvant therapy showed allelic retention in the Lsm1 region, whereas refractory cancers frequently showed allelic loss in this region." (PMID 11953827, 2002). "We examined the genes differentially expressed in advanced prostate cancers using cDNA-representational difference analysis (RDA), which is an efficient and reliable technique to isolate genes differentially expressed between samples to be compared, and thereby isolated the Lsm1 gene as one of them." (PMID 11953827, 2002).
glioma (3 papers, 2022 to 2023). A benign or malignant brain and spinal cord tumor that arises from glial cells (astrocytes, oligodendrocytes, ependymal cells). "Collectively, these findings indicate the prognostic significance of LSM1 in glioma, with increased LSM1 expression serving as an indicator of poorer clinical outcomes." (PMID 37954131, 2023). "To better evaluate the clinical impact of LSM1 expression, we next tested its effect on overall survival, disease-specific survival, and progression-free survival in glioma patients." (PMID 37954131, 2023). "We next investigated the levels of LSM1 expression in different glioma subtypes based on histological type, WHO grade, age, IDH status, and 1p/19q codeletion, which demonstrate the significant elevation of LSM1 expression in specific glioma subgroups." (PMID 37954131, 2023).
Cirrhosis (2 papers, 2020 to 2021). A chronic disorder of the liver in which liver tissue becomes scarred and is partially replaced by regenerative nodules and fibrotic tissue resulting in loss of liver function. "We observed decreased values of the LSM2/LSM1 ratio and the rate of cirrhosis progression in rs1801133 T allele carriers." (PMID 33304912, 2020). "The presence of the rs1801133 C allele showed an inverse association with the LSM2/LSM1 ratio (adjusted AMR = 0.90; 95%CI = 0.83–0.98; p = 0.020) and the cirrhosis progression (adjusted OR = 0.43; 95%CI = 0.19–0.95; p = 0.038)." (PMID 33304912, 2020). "A total of 26 patients developed cirrhosis (LSM1 ≥ 12.5) during a median follow-up of 46.6 months." (PMID 33304912, 2020). "Besides, rs1801133 CT/CC genotype had an inverse association with the LSM2/LSM1 ratio (adjusted AMR = 0.80; 95%CI = 0.68–0.95; p = 0.009) and the cirrhosis progression (adjusted OR= 0.21; 95%CI = 0.06–0.74; p = 0.015)." (PMID 33304912, 2020). "Moreover, rs886277 CC genotype was also related to higher values of LSM2/LSM1 ratio (adjusted arithmetic mean ratio a(AMR) = 1.31; p = 0.001) and cirrhosis progression (aOR = 4.33; p = 0.027)." (PMID 33525598, 2021).
colorectal cancer (2 papers, 2002 to 2023). A primary or metastatic malignant neoplasm that affects the colon or rectum. "Deletion of chromosome 8p11.2 has been frequently found in malignancies including stomach, kidney, urinary bladder and colorectal cancers, suggesting that Lsm1 gene is a candidate tumour suppressor or metastasis suppressor gene in common for a variety of human neoplasms." (PMID 11953827, 2002).
brain tumor (1 paper, 2023). "Our research sheds light on the potential oncogenic role of LSM1 in GBM and suggests its viability as a therapeutic target for this aggressive brain tumor." (PMID 37954131, 2023).
developmental delay (1 paper, 2019). "In conclusion, we report a homozygous splice variant in LSM1 that appears to be a founder Ashkenazi Jewish mutation that results in loss of expression of the canonical isoform in two siblings with global developmental delay, multiple congenital anomalies, and abnormal eye movements." (PMID 31010896, 2019). "Here, we report a homozygous splice variant in LSM1 (MIM 607281), encoding U6 snRNA-associated Sm-like protein LSm1, in two siblings with global developmental delay, multiple congenital anomalies affecting the heart, skeleton, and genitourinary system, and abnormal eye movements." (PMID 31010896, 2019).